KLF14 (KLF transcription factor 14)
Diseases named in the same sentence as KLF14 in open-access papers (continued):
Sharing a sentence is not in itself a finding about the gene and the disease.
iron deficiency (2 papers, 2007 to 2023). "Collectively, our results provide a novel therapy for HCC by fluphenazine administration which activated KLF14 causing iron deficiency and then suppresses cell growth in vitro and in vivo." (PMID 36600258, 2023). "Also, fluphenazine-treated tumors showed enhanced iron deficiency, apoptosis and inhibition of proliferation compared with fluphenazine-treated KLF14-silenced tumors." (PMID 36600258, 2023). "This prediction combined with the experimental observation that SP6/KLF14 is strongly induced by iron-deficiency suggests that SP6 could be involved in this genetic response." (PMID 18005439, 2007). "More important, we found fluphenazine is an activator of KLF14, inhibiting HCC cells growth through inducing iron deficiency." (PMID 36600258, 2023). "In conclusion, KLF14 inhibits the transcription of IRP2 via recruiting SIRT1, which then causes TfR1 downregulation and ferritin upregulation, resulting in cellular iron deficiency and suppression of HCC cells growth." (PMID 36600258, 2023).
liver cancer (2 papers, 2023 to 2024). An epithelial or non-epithelial malignant neoplasm that arises from the liver. "To further confirm that KLF14 inhibits the growth of liver cancer cells through interacting with SIRT1, we performed mutated KLF14 (KLF14-M4) stably overexpressed HCC cells." (PMID 36600258, 2023). "In liver cancer tissues, KLF14 expression is significantly downregulated, yet it accumulates at the VEPH1 promoter, enhancing VEPH1 transcription and protein expression." (PMID 39949609, 2024). "We generated KLF14 overexpressed and silenced liver cancer cells, and nude mouse xenograft models for the in vitro and in vivo study." (PMID 36600258, 2023). "Inhibition of KLF14 promoted liver cancer cells proliferation and overexpression of KLF14 suppressed cells growth." (PMID 36600258, 2023). "KLF14-overexpressed liver cancer cells displayed increased apoptosis rates, which was reversed with zinc finger 3 depleted." (PMID 36600258, 2023). "Furthermore, enhanced IRP2 expression restored the cellular LIP amount and cell growth in KLF14 overexpressed liver cancer cells." (PMID 36600258, 2023). "Moreover, mutation of KLF14 eliminated the suppression effects of full-length KLF14 on the growth and clonogenic formation of liver cancer cells." (PMID 36600258, 2023). "However, WWP1 ubiquitinates and degrades KLF14, which lacks a PY motif, suppressing VEPH1 expression and promoting liver cancer cell proliferation, invasion, and migration." (PMID 39949609, 2024). "Given that KLF14 induces cellular iron depletion and suppresses cell growth, we determined whether the modulation of cellular iron metabolism by IRP2 is important for the cell growth suppression in KLF14 overexpressed liver cancer cells." (PMID 36600258, 2023).
lymphoma (2 papers, 2015 to 2021). A malignant (clonal) proliferation of B- lymphocytes or T- lymphocytes which involves the lymph nodes, bone marrow and/or extranodal sites. "Preliminary results by our group suggest that KLF14 plays a tumor suppressing role in lymphoma, since a low expression of KLF14 is observed in the more aggressive lymphoma phenotypes." (PMID 33412518, 2021). "Of 27 KLF14-KO mice studied, 2 (7.4%) developed lung adenomas, 4 (14.8%) developed lymphoma in the spleens and 3 (11.1%) developed lymphoma in the lymph nodes, whereas no spontaneous tumour was identified in other organs such as the heart, liver, kidney, breast, colon and thymus." (PMID 26439168, 2015).
rectal cancer (2 papers, 2021). A primary or metastatic malignant neoplasm that affects the rectum. "LncRNA Hand2-AS1 competitively binds to miR-1275, targeting KLF14 to inhibit rectal cancer progression." (PMID 34118875, 2021).
astrocytomas (1 paper, 2022). "However, KLF14 expression was higher in astrocytomas relative to glioblastomas, and oligodendrogliomas while expression of miR-124 was higher in astrocytomas and oligodendrogliomas compared to glioblastomas." (PMID 35577881, 2022).
atherosclerotic heart diseases (1 paper, 2023). "Any alteration or dysregularities in KLF14 induce metabolic disorders such as T2DM and atherosclerotic heart diseases." (PMID 36837818, 2023).
autoimmune hepatitis (1 paper, 2022). Hepatitis caused by autoantibodies. "Other studies have shown that the upregulated expression of KLF14 protects the liver from immune-mediated damage by inducing Treg differentiation in autoimmune hepatitis (AIH)." (PMID 34983946, 2022).
Cerebral ischemia (1 paper, 2024). Restriction of arterial blood supply to the brain associated with insufficient oxygenation to support the metabolic requirements of the tissue. "In conclusion, KLF14 is a protective factor that is produced during cerebral ischemia-reperfusion injury." (PMID 38756375, 2024). "KLF14 was a protective factor produced during cerebral ischemia-reperfusion injury." (PMID 38756375, 2024).
cognitive decline (1 paper, 2023). "In addition, a previous study has implicated KLF14 in modulating gene expression in neurons, resulting in the reentry of the neuronal cell cycle and DNA damage responses under pathological conditions in AD, which may explain the protective role of KLF14 in cognitive decline." (PMID 37551728, 2023).
colitis (1 paper, 2022). Inflammation of the colon. "Recently, publications have shown that the transcription factor KLF14 can regulate the differentiation of Treg cells by binding to the Treg-specific demethylation region (TSDR) enhancer region, and the deletion of KLF14 was found to alleviate the inflammatory response in colitis induced by DSS." (PMID 34983946, 2022). "Previous observations have demonstrated that KLF14 is involved in T cell differentiation and that a lack of KLF14 results in protection against colitis, indicating that KLF14 is involved in the regulation of the immune response." (PMID 34983946, 2022).
endothelial dysfunction (1 paper, 2022). In vascular diseases, endothelial dysfunction is a systemic pathological state of the endothelium (the inner lining of blood vessels) and can be broadly defined as an imbalance between vasodilating and vasoconstricting substances produced by (or acting on) the endothelium. "The deregulation of the KLF14/PLK1 cascade plays a crucial role in thrombin-induced endothelial dysfunction in T2DM patients." (PMID 36046788, 2022).
glioma (1 paper, 2022). A benign or malignant brain and spinal cord tumor that arises from glial cells (astrocytes, oligodendrocytes, ependymal cells). "Expression analysis of TPD52, KLF14, miR-124, and PKCε provided useful information on the differences existing between the normal brain and SOL, in addition to gliomas; thus, might prove to be useful having diagnostic or prognostic value." (PMID 35577881, 2022). "Thus, in the present study we aimed to predict KLF14 three-dimensional structure to contribute information about its function and differences that may exist between normal brain, SOL of brain and gliomas." (PMID 35577881, 2022).
Hepatic steatosis (1 paper, 2025). Steatosis is a term used to denote lipid accumulation within hepatocytes. "They observed that KLF14‐AAV mice gained less weight, had greater expression of browning genes, had decreased markers of hepatic steatosis, had improved glycemic tolerances, and had smaller adipocytes." (PMID 40790397, 2025).
Infertility (1 paper, 2025). "In our study, we sought to investigate the possible involvement of the ELOVL2, TRIM59, C1orf132, FHL2, and KLF14 genes in reproductive aging, infertility, and outcomes of ART." (PMID 40558830, 2025).
ischemic stroke (1 paper, 2024). A stroke disorder caused by obstruction of blood flow to the brain, due to thrombotic (local blood clot formation) or embolic (due to a blood clot or other material traveling from another site) event. "Neurons are susceptible to damage after ischemic stroke, and it is of great importance to study them, so in the present study we examined the changes in KLF14 expression in neuronal cells after ischemia-reperfusion injury." (PMID 38756375, 2024). "Collectively, H-EXOs exerted anti-inflammatory effects in neurons after ischemic stroke via upregulating the expression of KLF14." (PMID 38756375, 2024). "Overall, H-EXOs exerted anti-inflammatory effects in neurons after ischemic stroke via upregulating the expression of KLF14." (PMID 38756375, 2024). "In conclusion, our research suggests that KLF14 might be a potential target for the treatment of cerebral ischemic injury, and H-EXOs are promising to be a therapeutic strategy for ischemic stroke." (PMID 38756375, 2024).
large-cell lymphoma (1 paper, 2015). "Conversely, Plk4 transcription showed a downregulation pattern in the anaplastic lymphoma kinase-negative anaplastic large-cell lymphoma (Eckerle lymphoma data set), which showed a clear upregulation of KLF14 transcription." (PMID 26439168, 2015).
lipodystrophy (1 paper, 2022). A congenital or acquired disorder characterized by abnormal loss or redistribution of the adipose tissue in the body. "For example, we saw adipose-specific TG and HDL colocalizations for both KLF14 and LPL, two genes assigned previously to a lipodystrophy cluster that has been shown to overlap with IR biology." (PMID 35292083, 2022).
lung carcinoma (1 paper, 2024). "In addition to KLF1, KLF13, KLF14 and KLF16 or KLF18 (?)with machine learning prediction waiting for verification, many KLFs have been found to be associated with the progress of lung cancer by activating or inhibiting target gene expression." (PMID 38560274, 2024). "However, up to now, whether some KLFs (KLF1, KLF13, KLF14 and KLF16) with unknown functions are involved in the progressions of lung cancer have not been fully understood, and remain to be explored or verified at the levels of cell, tissue and animal models." (PMID 38560274, 2024).
pancreatic cancer (1 paper, 2021). "Subsequently, they found that KLF14 transrepressed Cyclin A2 promoter in pancreatic cancer cell lines." (PMID 34031939, 2021).
psychosis (1 paper, 2023). "The fact that methylation of KLF14 correlates with psychosis severity in schizophrenia patients strengthens our argument for the applicability of HFP chickens in the research of the basic mechanisms involved in human psychiatric disorders." (PMID 36449109, 2023).
tumor (22 papers, 2015 to 2024). "For CRC106, the final tumor masses were 1.46‐ and 1.83‐fold higher in KLF14‐deficient PDOX and 3.26‐ and 2.25‐fold higher in EGR2‐deficient PDOX compared to the scrambled control group." (PMID 38380561, 2024). "Recently, KLF14 has also been found to be associated with the occurrence and progression of tumours." (PMID 35570248, 2022). "Loss of KLF14 leads to centrosome amplification, genome instability and spontaneous tumour formation." (PMID 31406196, 2019). "Loss of KLF14 leads to centrosome amplification, genome instability and most importantly spontaneous tumour formation." (PMID 26439168, 2015). "The CpGs constituting the FCC were primarily associated with the two known aging genes ELOLV2 and KLF14, linked to metabolism, which were hypermethylated, followed by a tumour suppressing gene RNF180, and DYTN, a gene with unknown function, that were both hypomethylated." (PMID 39695947, 2024). "For CRC187, the final tumor masses of KLF14‐shRNA1, KLF14‐shRNA2, EGR2‐shRNA1, and EGR2‐shRNA2 were 2.84‐, 2.18‐, 2.87‐, and 1.90‐fold higher than control PDOX, respectively." (PMID 38380561, 2024). "In particular, KLF14 has been identified as a key factor restraining tumor proliferation and invasion in colorectal cancer." (PMID 38892411, 2024). "KLF14 exerts its anti-tumor function by inhibiting Iron-responsive element-binding protein 2 (IRP2), which then causes transferrin receptor-1(TfR1) downregulation and ferritin upregulation on the basis of IRP-IREs system." (PMID 36600258, 2023). "IHC staining of KLF14 in HCC samples further confirmed that 71.1% of samples presented a significantly lower expression in tumor tissues than that in paired adjacent tissues." (PMID 36600258, 2023). "And injection of fluphenazine significantly inhibited the growth of tumor while silencing of KLF14 attenuated the suppression effect, which were consistent with results the in vitro." (PMID 36600258, 2023). "KLF14-mediated the suppression of IRP2 was dependent on SIRT1, which suggests a KLF14-related epigenetic mechanism in the regulation of iron homeostasis and tumor growth in HCC." (PMID 36600258, 2023). "KLF14 acts as a tumor suppressor which inhibits the proliferation of HCC cells by modulating cellular iron metabolism via the repression of IRP2." (PMID 36600258, 2023). "In summary, our study firstly demonstrated that KLF14 acts as a tumor suppressor in HCC and inhibits the HCC cells growth through reducing cellular LIP contents by suppressing IRP2." (PMID 36600258, 2023). "The study further expands our understanding of the upstream transcription regulatory mechanism of IRP2 by KLF14 as well as the crucial role of IRP2 in the tumor cell iron metabolism and it would be helpful for the understanding of the progression of HCC." (PMID 36600258, 2023). "The results showed that the mRNA level of KLF14 was significantly down-regulated in HCC tumor tissues compared with adjacent tissues." (PMID 36600258, 2023). "For further verification, we explored the expression of KLF14 and other related molecules in tumour tissues." (PMID 35570248, 2022). "This study further focuses on the expression of KLF14 in relation with metastatic status and tumor grade." (PMID 35577881, 2022). "In vivo results confirmed that subcutaneous tumours in the KLF14-overexpression group were smaller, lower in weight, and grew more slowly than those in the Lv-control group." (PMID 35570248, 2022). "We observed an additional tumour with integration in KLF14 located in 7q32.3, one in KLF4 located in 9q31.2, and one in KLF6 located in 10p15.1." (PMID 35398964, 2022). "The results showed that tumours in the Lv-KLF14 group were smaller than those in the Lv-control group." (PMID 35570248, 2022). "CircTADA2A blocked the cell cycle, glycolysis and tumor growth while triggered the apoptosis of CRC cells through up-regulating KLF14 via targeting miR-374a-3p." (PMID 32799891, 2020).
tumor (continued). "They proposed that KLF14 plays a tumor suppressor role, since Klf14 transcription is significantly downregulated in multiple types of cancers." (PMID 32548128, 2020). "Epcam+ cells were enriched for tumor-related motifs Klf14, Mitf, Ets1, Nrf2, and Nrf1 binding motifs." (PMID 31594952, 2019). "Correlational analysis revealed a significant negative correlation between the protein expression levels of KLF14 and Plk4 in both breast and colon tumour tissues (Spearman's ρ=−0.6 and −0.8, respectively)." (PMID 26439168, 2015). "In this study, we disrupted the KLF14 gene in mice and report that KLF14 serves as a novel tumour suppressor essential for limiting Plk4-directed centrosome amplification." (PMID 26439168, 2015). "Collectively, our findings identify KLF14 as a tumour suppressor and highlight its potential as biomarker and therapeutic target for cancer." (PMID 26439168, 2015). "One of the study reveal that KLF14 reduction serves as a mechanism leading to centrosome amplification and tumorigenesis and further indicated that KLF14 serves as a tumour suppressor and reported its potential as biomarker and therapeutic target for several malignancies." (PMID 36831624, 2023). "Results showed that KLF14 was downregulated in HCC tumor tissues and most HCC cell lines." (PMID 36600258, 2023). "Importantly, KLF14 showed a lower expression in breast cancer and colorectal cancer indicating a tumor suppression effect." (PMID 36600258, 2023). "The down regulation of the KLF14 in cancers suggested that it has an anti-tumour role." (PMID 36831624, 2023). "Besides, Immunohistochemical images of the adjacent normal tissues and tumor tissues in HCC patients exhibited that the expression of KLF14 is lower in HCC tumor tissues together with higher IRP2 expression and iron concentration." (PMID 36600258, 2023). "Furthermore, in the in vivo experiment, we detected the expression of relevant molecules in tumour tissues, including KLF14, ITGB1, p-AKT (a key molecule in the PI3K/AKT signalling pathway), and cleaved caspase-3 (an apoptosis marker)." (PMID 35570248, 2022). "The tumours in the Lv-control group grew faster than those in the Lv-KLF14 group." (PMID 35570248, 2022). "The tumour weight in the Lv-KLF14 group was significantly lower than that in the Lv-control group." (PMID 35570248, 2022). "Furthermore, KLF14 was involved in proliferation, survival and migration in several tumour cells, and KLF14 mainly exerted inhibitory roles in these cellular processes, and functioned as a protective factor." (PMID 34031939, 2021). "KLF14 has been reported to be a tumor suppressor in diverse cancers." (PMID 32799891, 2020). "To analyse the tumour suppressive activity of KLF14, we generated MEFs from 13.5-day-old embryos." (PMID 26439168, 2015). "As no tumour was detected in WT mice during this period, we conclude that loss of KLF14 leads to spontaneous tumorigenesis in adult mice." (PMID 26439168, 2015). "Importantly, the KLF14-KO mice showed a marked increase in tumour number and size, and the number of high-grade tumours was significantly higher in KLF14-KO mice." (PMID 26439168, 2015). "Indeed, the spontaneous tumours from KLF14-KO mice displayed high levels of Plk4 expression and centrosome amplification compared with WT mouse tissues." (PMID 26439168, 2015). "In this context, KLF14, a member of the KLF family, emerges as a crucial regulator of the immune system and tumor development." (PMID 38892411, 2024). "Among them, KLF14 and EGR2 footprints are enriched in PDOX relative to matched PDO, and silencing of KLF14 or EGR2 promoted tumor growth." (PMID 38380561, 2024). "CircTADA2A functioned as a tumor suppressor in CRC to inhibit the glycolysis and cell cycle and potentiate the apoptosis of CRC cells via miR-374a-3p/KLF14 axis." (PMID 32799891, 2020). "Eight pairs of 8-week-old KLF14-WT and -KO mice were placed on the AOM/DSS protocol and the tumour formation was checked 6 weeks after the last DSS cycle." (PMID 26439168, 2015).
tumor (continued). "Furthermore, EPHA4, a shared downstream target gene of KLF14 and EGR2, altered tumor sensitivity to MEK inhibitor treatment." (PMID 38380561, 2024). "Therefore, KLF14 and EGR2 binding activities were upregulated by the in vivo environment, and reducing KLF14 and EGR2 resulted in enhanced tumor growth." (PMID 38380561, 2024). "As KLF14 knockdown mediates an increase of iron concentration through elevating the expression of IRP2, we suggested KLF14 reduction contributes to IRP2 elevation and excessive iron in HCC tumor tissues." (PMID 36600258, 2023). "Besides, KLF14 expression was significantly correlated with tumor size, TNM stage, serum AFP level and portal vein tumor thrombus (PVTT) in patients with HCC." (PMID 36600258, 2023). "The ectopic expression of circTADA2A could restrain the tumor growth, cell cycle and glycolysis and promote the apoptosis of CRC cells through miR-374a-3p/KLF14 axis." (PMID 32799891, 2020). "KLF14-KO mice were viable and showed no obvious abnormality in body weight and serum lipids, but developed spontaneous tumours over time." (PMID 26439168, 2015). "Therefore, the differential binding of KLF14 and EGR2 and expression of downstream EPHA4 impact both tumor growth and drug sensitivity, suggesting that chromatin remodeling in different PDMC may interfere with their ability to predict therapeutic outcomes." (PMID 38380561, 2024). "A notable negative correlation between the mRNA levels of KLF14 and IRP2 was observed in tumor tissues." (PMID 36600258, 2023).